ATXN2 (ataxin 2)
Diseases named in the same sentence as ATXN2 in open-access papers (continued):
Sharing a sentence is not in itself a finding about the gene and the disease.
spinocerebellar ataxia type 2 (continued). "The function of ataxin-2 is unknown; however, the expansion of polyglutamine tracts may cause spinocerebellar ataxia type 2 (SCA2)." (PMID 36248971, 2022). "For example, ataxin-2, the product of the spinocerebellar ataxia type 2 gene, contains 22 glutamines and resides in the Golgi apparatus." (PMID 34884222, 2021). "The spinocerebellar ataxia type 2 (SCA2) gene ATXN2 has a prominent role in the pathogenesis and treatment of amyotrophic lateral sclerosis (ALS)." (PMID 32307524, 2020). "Spinocerebellar ataxia type 2 (SCA2) is caused by polyglutamine expansion in Ataxin-2 (ATXN2)." (PMID 32932600, 2020). "Spinocerebellar ataxia type 2 (SCA2, OMIM 183090) is an autosomal dominant inherited disease caused by trinucleotide repeat expansion in the coding region of ATXN2 gene." (PMID 33384659, 2020). "Conversely, the progressive ATXN2 gain of function due to the fact of polyglutamine (polyQ) expansions leads to a dominantly inherited neurodegenerative process named spinocerebellar ataxia type 2 (SCA2) with early adipose tissue loss and late muscle atrophy." (PMID 31766565, 2019). "Among these, spinocerebellar ataxia type 2 (SCA2), one of the most frequent types, is definitely caused by an CAG repeat expansion in the ATXN2 gene." (PMID 30125476, 2018). "Secondly, the patients with slow saccades who were the basis of our local feedback model of control of saccades, turned out to have spinocerebellar ataxia type 2 (SCA2) with an abnormality on chromosome 12 (ATXN2 gene)." (PMID 29445510, 2018). "Spinocerebellar ataxia type 2 (SCA2) is an autosomal-dominant, adult-onset neurodegenerative disease caused by a polyglutamine expansion in the ataxin-2 gene (ATXN2)." (PMID 28982376, 2017). "Spinocerebellar ataxia type 2 (SCA2) is an autosomal dominant disorder with progressive degeneration of cerebellar Purkinje cells (PCs) and other neurons caused by expansion of a glutamine (Q) tract in the ATXN2 protein." (PMID 25902068, 2015). "Long polyglutamine tracts, including more than 34 CAG repeats in the ataxin 2 (ATXN2) gene, have been identified as a cause of spinocerebellar ataxia type 2 (SCA2)." (PMID 26213621, 2015). "In ATXN2, polyQ expansions of ≥34, which are pure CAG repeat expansions, cause spinocerebellar ataxia type 2." (PMID 21479228, 2011). "Importantly, the stability of the CAG repeat sequence in ATXN2 is influenced by CAA disruption, leading to allelic instability and the pathogenic expansion observed in spinocerebellar ataxia type 2 (SCA2)." (PMID 39039334, 2024). "Ataxin-2 (Atx2) is a polyglutamine (polyQ) tract-containing RNA-binding protein, while its polyQ expansion may cause protein aggregation that is implicated in the pathogenesis of neurodegenerative diseases such as spinocerebellar ataxia type 2 (SCA2)." (PMID 38810698, 2024). "Moreover, in a murine model of spinocerebellar ataxia type 2, it has been possible to show how pathological aggregation of Ataxin-2 (Atxn2) results in inclusions with sequestered TIA1." (PMID 35163320, 2022). "Type 2 spinocerebellar ataxia (SCA2) is one of the autosomal dominant cerebellar ataxias and is caused by a CAG repeat expansion in ATXN2 resulting in progressive cerebellar ataxia and other neurological signs and symptoms, including ocular motor abnormalities." (PMID 36209056, 2022). "Spinocerebellar ataxia type-2 (SCA-2) is the commonest worldwide and mostly in India and has an autosomal dominant inheritance where translated protein, Ataxin-2 causes neuronal apoptotic cell death of cerebellum, pons, hypothalamus, and spinal cord related to autonomic control." (PMID 34873557, 2021). "Spinocerebellar ataxia type 2 (SCA2) is an inherited disorder caused by polyglutamine (polyQ) tract expansions secondary to mutations of the ATXN2 gene (coding for the Ataxin-2 protein); these polyQ expansions are encoded at the DNA level in ATXN2 by trinucleotide CAG repeats." (PMID 29342921, 2018).
spinocerebellar ataxia type 2 (continued). "Further, Ataxin 2, an ALS-linked RBP that causes spinocerebellar ataxia type 2 (SCA2), is associated to SGs and might have a role in their assembly." (PMID 28386218, 2017). "Spinocerebellar ataxia type 2 (SCA2) and amyotrophic lateral sclerosis (ALS) are neurodegenerative disorders, caused or modified by an unstable CAG-repeat expansion in the SCA2 gene, which encodes a polyglutamine (polyQ) domain expansion in ataxin-2 (ATXN2)." (PMID 25721894, 2015). "Although many genes exhibited high editing rate in terms of number of events per locus, RBFOX1 appeared the most edited comprising 142 Alu elements and coding for a RNA-binding protein able to interact with the ataxin-2 which is involved in the familial form of spinocerebellar ataxia type 2 (SCA2)." (PMID 26449202, 2015). "This protein binds to the C-terminus of ataxin-2 and may contribute to the restricted pathology of spinocerebellar ataxia type 2 (SCA2)." (PMID 19508968, 2009). "Ataxin 2 (Atxn2), mutations of which are found in ALS13 and spinocerebellar ataxia type 2 (SCA2), was also listed within the category (a)." (PMID 40271315, 2025). "Spinocerebellar ataxia type 2 (SCA2) and amyotrophic lateral sclerosis (ALS) are both associated with a CAG-repeat expansion in ATXN2 and with the development of TDP-43-positive neuronal cytoplasmic inclusions." (PMID 39956874, 2025). "Interestingly, this analysis revealed that the coverage and the genotyping quality for coding RED loci were good (>20×) across all genes, with the exception of CACNA1A, ATXN2 and HTT, which cause spinocerebellar ataxia 2, spinocerebellar ataxia 6 and Huntington disease, respectively." (PMID 40004498, 2025). "For ATXN2, intermediate expansions (29–33 repeats) are associated with ALS risk while expansions > 33 repeats cause spinocerebellar ataxia type 2 (SCA2), a neurodegenerative disease which primarily affects cerebellar Purkinje neurons." (PMID 40275359, 2025). "Due to the genetic instability of a glutamine domain (polyQ) in ATXN2 across generations, an abnormally expanded polyQ in ATXN2 (>Q35) plays an important role in spinocerebellar ataxia type 2 (SCA2)." (PMID 41462986, 2025). "It has been established that the expansion of trinucleotide repeats in ATXN2 can result in spinocerebellar ataxia type 2 (SCA2)." (PMID 39232780, 2024). "Expansion of the polyglutamine tract in the human ATXN2 gene leads to spinocerebellar ataxia type 2 (SCA2)." (PMID 34983696, 2022). "A similar relationship between morphology-regulating proteins, ER dynamics and disease is observed with ataxin-2 in spinocerebellar ataxia type 2 (SCA2)." (PMID 34571990, 2021). "ATXN2 is a 140 kDa protein that has mainly been studied as a polyglutamine repeat protein in the context of spinocerebellar ataxia type 2 (SCA2) and amyotrophic lateral sclerosis (ALS)." (PMID 32024018, 2020). "Ataxin-2 is an evolutionarily conserved protein first identified in humans as responsible for spinocerebellar ataxia type 2 (SCA2)." (PMID 25027299, 2014). "An expansion of the polyglutamine (polyQ) tract in Ataxin-2 was identified as responsible for spinocerebellar ataxia type 2 (SCA2), a progressive neurodegenerative disease." (PMID 25027299, 2014). "However, when the CAG trinucleotide repeats in the ATXN2 gene are abnormally amplified to an intermediate length (>23), it can lead to ALS pathology; when the CAG is further abnormally amplified (>33), it may cause spinocerebellar ataxia type 2 (SCA2)." (PMID 41373690, 2025). "ATXN2 has also been implicated in the pathology of ALS and Spinocerebellar Ataxia Type 2 (SCA2)." (PMID 40430041, 2025). "Spinocerebellar ataxia type 2 (SCA2) is autosomal dominantly inherited and caused by DNA CAG repeat expansion leading to an increase in the polyglutamine (polyQ) domain in the N‐terminal part of the ATXN2 protein." (PMID 37072935, 2023).
spinocerebellar ataxia type 2 (continued). "The long trinucleotide repeats expansions (≥36) in ATXN2 have been known to be related to spinocerebellar ataxia type 2 (SCA2), but the intermediate length expansions (27–33 repeats) were also discovered to increase susceptibility to ALS, not only in FALS but also in SALS." (PMID 35754054, 2022). "This raises the question of whether motor neuron disease is part of the spectrum of that particular form of cerebellar ataxia and sensory neuronopathy, as is the case with ATXN2 spinocerebellar ataxia type 2 (SCA2)." (PMID 36555161, 2022). "Spinocerebellar ataxia type 2 (SCA2) is a rare and fatal dominantly-inherited polyglutamine (polyQ) disease, being caused by abnormal repeats of the triplet CAG in the ATXN2 gene, resulting in an expanded polyQ chain in the ataxin-2 protein." (PMID 34845184, 2021). "Spinocerebellar ataxia type 2 (SCA2) and type 3 (SCA3) are PolyQ diseases in which the Ataxin-2 and Ataxin-3 proteins, respectively, contain an abnormal polyQ tract prone to aggregate." (PMID 33530161, 2021). "The Ataxin-2 (Atx2) protein contributes to the progression of neurodegenerative phenotypes in animal models of amyotrophic lateral sclerosis (ALS), type 2 spinocerebellar ataxia (SCA-2), Parkinson’s disease, and Huntington’s disease (HD)." (PMID 34718534, 2021). "Furthermore, repeat expansions in the gene encoding ataxin 2 (ATXN2), which cause spinocerebellar ataxia type 2 (SCA2), are also increased in ALS patients compared to healthy controls." (PMID 31316328, 2019). "Moreover, intermediate-length polyQ expansions in ataxin-2 (ATXN2) are associated with an increased risk of ALS, while expansions of >34 repeats cause spinocerebellar ataxia type 2 (SCA-2)." (PMID 29570669, 2018). "ATXN2 is a poly-glutamine repeat containing protein involved in many neurodegenerative disorders such as amyotrophic lateral sclerosis (ALS) and Spinocerebellar Ataxia type 2 (SCA2)." (PMID 26677855, 2015). "Transgenic mice carrying the human ataxin-2 gene, with an enlarged CAG repeat sequence, are used as a model of human spinocerebellar ataxia type 2 (SCA2)." (PMID 26331028, 2014). "Spinocerebellar ataxia type 1 (SCA1), spinocerebellar ataxia type 2 (SCA2) and Huntington disease are autosomal-dominant genetically determined neurodegenerative diseases, caused by the expanded CAG repeats (polyglutamine, polyQ) at the ATXN1, ATXN2 and HTT genes, respectively." (PMID 39974178, 2025). "None of the patients with repeat expansions in ATXN2 or HTT had signs of Huntington’s disease or spinocerebellar ataxia type 2, based on a re-evaluation of medical records." (PMID 38585669, 2024). "Human ataxin-2 (Atx2, also abbreviated to ATXN2) is such a polyQ tract-containing protein; expansion of the polyQ tract in Atx2 can trigger protein aggregation that may cause neurodegenerative diseases like spinocerebellar ataxia type 2 (SCA2)." (PMID 38810698, 2024). "Interestingly, an interaction between FOX-1 and ataxin-2 (ATXN2), the disease protein in another SCA, spinocerebellar ataxia type 2 (SCA2), has been reported as well." (PMID 22666429, 2012). "Spinocerebellar Ataxia type 2 (SCA2) and Amyotrophic Lateral Sclerosis type 13 (ALS13) are triggered by polyglutamine expansion in Ataxin-2 (ATXN2)." (PMID 42041567, 2026). "Ataxin-2 (human gene symbol ATXN2, protein ATXN2), a polyglutamine repeat protein, is the autosomal dominant neurodegenerative disorder disease protein of spinocerebellar ataxia type 2 (SCA2)." (PMID 41153762, 2025). "Spinocerebellar ataxia type 2 (SCA2) is an autosomal dominantly inherited neurodegenerative disease, which belongs to the trinucleotide repeat disease group with a CAG repeat expansion in exon 1 of the ATXN2 gene resulting in an ataxin-2 protein with an expanded polyglutamine (polyQ)-stretch." (PMID 36894829, 2023).
amyotrophic lateral sclerosis (88 papers, 2014 to 2026). Amyotrophic lateral sclerosis (ALS) is a neurodegenerative disease characterized by progressive muscular paralysis reflecting degeneration of motor neurons in the primary motor cortex, corticospinal tracts, brainstem and spinal cord. "ATXN2 and TBP were also associated with susceptibility to Parkinson disease, a common neurological disorder, while ATXN2 was also associated with susceptibility to amyotrophic lateral sclerosis (ALS), a neurodegenerative disease." (PMID 41254939, 2025). "ATXN2 repeat alleles cover the range from recessive and dominant mendelian alleles to risk alleles for amyotrophic lateral sclerosis." (PMID 39872677, 2025). "Our findings indicate that repeat expansions in HTT and ATXN2 are associated with increased likelihood of developing amyotrophic lateral sclerosis." (PMID 38585669, 2024). "In 2010, intermediate-length repeat expansions in ATXN2 were reported to be a risk factor for amyotrophic lateral sclerosis, and in 2012, the same was reported for ATXN1." (PMID 38585669, 2024). "Ataxin-2 is a protein containing a polyQ extension and intermediate length of polyQ extensions increases the risk of Amyotrophic Lateral Sclerosis (ALS)." (PMID 39739690, 2024). "Results indicate an increased risk of amyotrophic lateral sclerosis if carrying repeat expansions in ATXN2 and HTT." (PMID 38585669, 2024). "In this cohort study, HTT and ATXN2 repeat expansions were associated with an increased risk of developing amyotrophic lateral sclerosis." (PMID 38585669, 2024). "Repeat expansions in genes other than C9orf72 and ATXN2 have been recently associated with Amyotrophic Lateral Sclerosis (ALS)." (PMID 36823368, 2023). "Ataxin-2 (Atx2) is a translational control molecule mutated in spinocerebellar ataxia type II and amyotrophic lateral sclerosis." (PMID 33689682, 2021). "Recent research has also demonstrated ataxin-2 to act as risk factor in the motor neuron degenerative disease Amyotrophic Lateral Sclerosis (ALS), in RNA-mediated interaction with the splicing modulator TDP-43." (PMID 33324888, 2019). "Diseases associated with ATXN2 included cardiovascular disease, thrombotic antiphospholipid syndrome, and amyotrophic lateral sclerosis, and others." (PMID 25820152, 2015). "Repeat expansion analyses were performed for 414 amyotrophic lateral sclerosis patients and 713 neurologically normal controls; pathogenic and intermediate-length repeat expansions in AR, ATXN2 and HTT were observed in 3.1% of the amyotrophic lateral sclerosis patients." (PMID 38585669, 2024). "Interestingly, polyQ repeat expansions in ATXN2 are also associated with amyotrophic lateral sclerosis (ALS) and parkinsonism depending upon the length of the polyQ repeat expansion." (PMID 34077532, 2021). "Trinucleotide CAG expansions of the ataxin‐2 protein, encoded by the ATXN2 gene, increase the susceptibility to amyotrophic lateral sclerosis; in contrast, prolonged expansion leads to spinocerebellar ataxia‐2 (SCA2), an autosomal dominant neurodegenerative disease." (PMID 31386307, 2019). "Currently, the recognition of signs of lower motor neuron degeneration in SCA2 acquires additional clinical and pathogenetic relevance given the known relationship between the intermediate alleles of ATXN2 gene and increased risk of amyotrophic lateral sclerosis (ALS)." (PMID 28955296, 2017). "Intermediate Q27–Q33 expansions in ATXN2 are associated with the risk of amyotrophic lateral sclerosis (ALS) and frontotemporal lobar dementia (FTLD), with tauopathies and Parkinson’s variants such as progressive supranuclear palsy (PSP)." (PMID 41462986, 2025). "Repeat expansions, including those in C9orf72 and ATXN2, have been implicated in amyotrophic lateral sclerosis (ALS)." (PMID 35599735, 2022).
amyotrophic lateral sclerosis (continued). "Importantly, many RBPs have been shown to have strong genetic links to neurodegenerative disease; for example, mutations in TDP-43, FUS, hnRNPA1, and ATXN2 have all been shown to cause amyotrophic lateral sclerosis (ALS), frontotemporal lobar degeneration (FTLD) and/or spinocerebellar ataxia." (PMID 30068389, 2018). "A decade later, certain polyQ expansions of ATXN2 were also linked to the devastating and too often fatal motor neuron disease known as amyotrophic lateral sclerosis (ALS)." (PMID 28587229, 2017). "Recent data support the hypothesis that ATXN2-IA increased the risk of amyotrophic lateral sclerosis (ALS) and of frontotemporal dementia." (PMID 37906407, 2024). "Ataxin-2 (ATXN2) is a gene implicated in spinocerebellar ataxia type II (SCA2), amyotrophic lateral sclerosis (ALS) and Parkinsonism." (PMID 38768217, 2024). "We identified seven amyotrophic lateral sclerosis patients (1.7%) carrying ≥29 repeats (29, 29, 30, 30, 31, 33 and 34) in ATXN2 compared to three (0.4%) in the control group (31, 31 and 34 repeats) (OR 4.8, 95% CI 1.1–21.2, P = 0.04)." (PMID 38585669, 2024). "ATXN2 is a large pleiotropic gene involved in various age-related diseases, including type 2 diabetes, high blood pressure, amyotrophic lateral sclerosis, and inflammation." (PMID 34858478, 2021). "Interestingly, both TARDBP and ATXN2 are implicated in neurological disorders such as amyotrophic lateral sclerosis (ALS); in addition, Ataxin-2 has been implicated in microRNA regulation." (PMID 33101370, 2020). "We investigated a CAG trinucleotide repeat expansion in the ATXN2 gene in amyotrophic lateral sclerosis (ALS)." (PMID 28017481, 2017). "It will be particularly important to determine if the effects of ATXN2 polyQ expansions on the motor neuron degeneration in amyotrophic lateral sclerosis has shared pathogenesis pathways." (PMID 26868665, 2017). "Recent studies have identified the RNA-binding protein Ataxin-2 as a genetic determinant or risk factor for various diseases including spinocerebellar ataxia type II (SCA2) and amyotrophic lateral sclerosis (ALS), amongst others." (PMID 28587229, 2017). "Finally, Pbp1 is the yeast homolog of ataxin-2, a well-known genetic modifier of amyotrophic lateral sclerosis and spinocerebellar ataxia in humans." (PMID 40801888, 2025). "A small number of individuals with ATXN2 mutations present with outlier phenotypes such as l-DOPA responsive parkinsonism or amyotrophic lateral sclerosis (ALS) indistinguishable from idiopathic forms of the respective diseases." (PMID 39872677, 2025). "IAs in the ATXN2 and ATXN1 genes may cause amyotrophic lateral sclerosis, and grey zone alleles of the FMR1 have been associated with parkinsonism." (PMID 38433266, 2024). "Abnormal ATXN2 splicing and alternative polyadenylation were documented in diseases with RNA toxicity, such as amyotrophic lateral sclerosis (ALS)." (PMID 32698485, 2020). "Genetic analyses of patients with amyotrophic lateral sclerosis (ALS) have revealed a strong association between mutations in genes encoding many RNA-binding proteins (RBPs), including TARDBP, FUS, hnRNPA1, hnRNPA2B1, MATR3, ATXN2, TAF15, TIA-1, and EWSR1, and disease onset/progression." (PMID 32547363, 2020). "Deletion of the ATXN2 ortholog, PBP1, reduces yeast TDP-43 toxicity, which led to identification of ATXN2 as an amyotrophic lateral sclerosis (ALS) risk factor and therapeutic target." (PMID 31390360, 2019). "Given that Ataxin-2 interacts with crucial splice modulators such as TDP-43 and modulates the risk of Amyotrophic Lateral Sclerosis, its own splice isoforms may become relevant in brain tissue to monitor the RNA processing during disease progression and neuroprotective therapy." (PMID 33324888, 2019).